DLX6-AS1 (DLX6 antisense RNA 1)
Synonyms: uc.221; uc.220; FLJ34048; Evf-2; formerly NCRNA00212
Gene: Long non-coding RNA gene on chromosome 7 (96,955,141 to 97,014,088, reverse strand). Ensembl gene ENSG00000231764.
Gene Ontology:
Biological process: forebrain development; positive regulation of DNA-templated transcription
Diseases named in the same sentence as DLX6-AS1 in open-access papers:
DLX6-AS1 is named in the same sentence as 14 diseases in open-access papers, as found by Europe PMC text mining. Sharing a sentence is not in itself a finding about the gene and the disease. The quoted sentences say what the papers report.
bladder cancer (1 paper, 2019). "In this study, we evaluated the expression of DLX6 Antisense RNA 1 (DLX6-AS1) in the cancerous bladder tissues and studied the possible mechanisms of DLX6-AS1 in regulating bladder cancer progression." (PMID 31787849, 2019). "Recently, the lncRNA DLX6 Antisense RNA 1 (DLX6-AS1) has been found to be dysregulated in several types of malignant tumors, however, to our best knowledge, the expression profiles of DLX6-AS1 have been not determined in the bladder cancer yet." (PMID 31787849, 2019).
endometrial cancer (1 paper, 2020). Primary or metastatic malignant neoplasm involving the endometrium (mucous membrane that lines the endometrial cavity). "The aim of the present study was to identify the molecular mechanisms of the lncRNA known as DLX6 antisense RNA 1 (DLX6‐AS1) in endometrial cancer." (PMID 32951317, 2020).
myocardial infarction (1 paper, 2013). Gross necrosis of the myocardium, as a result of interruption of the blood supply to the area, as in coronary thrombosis. "A handful of lncRNAs are conserved while other well-characterized functional mammalian lncRNAs, such as myocardial infarction associated transcript (Gomafu), Dlx6 antisense RNA 1 (Evf-2) and HOX transcript antisense RNA (HOTAIR) exhibit poor sequence conservation across species." (PMID 24961318, 2013).
pancreatic cancer (1 paper, 2018). "This study aimed to determine the expression of lncRNA DLX6 antisense RNA 1 (DLX6-AS1) in pancreatic cancer tissues and to explore the DLX6-AS1-related pathway in pancreatic cancer." (PMID 30250401, 2018).
thyroid carcinoma (1 paper, 2021). "Long non‐coding RNA DLX6 antisense RNA 1 (DLX6‐AS1) lists a critical position in thyroid carcinoma (TC) development." (PMID 34514705, 2021).
triple-negative breast carcinoma (1 paper, 2021). An invasive breast carcinoma which is negative for expression of estrogen receptor (ER), progesterone receptor (PR), and human epidermal growth factor receptor 2 (HER2). "In triple-negative breast cancer, the lncRNA DLX6 antisense RNA 1 was upregulated in cancer tissues, and its expression promoted cell proliferation, EMT, and cisplatin resistance by regulating the miR-199b-5p/PXN axis." (PMID 34946859, 2021).
DLX6-AS1 also shares sentences with these, for which no sentence is quoted: diabetic nephropathy (3 papers); cancer (2); gastric cancer (1); kidney diseases (1); melanoma (1); neurological disorders (1); prostate carcinoma (1); tumor (1).